TF (transferrin)
Diseases named in the same sentence as TF in open-access papers (continued):
Sharing a sentence is not in itself a finding about the gene and the disease.
anemia (continued). "Third, the definition of anemia in the present study lacks other parameters such as serum iron, ferritin, transferrin saturation, and total iron-binding capacity." (PMID 34789178, 2021). "A collection of anemia-related biomarkers, such as ferritin and transferrin saturation, would also be relevant to differentiate patients according to the type of anemia." (PMID 34830693, 2021). "We estimated the IDA prevalence and the contribution of ID to anemia, and the former 7.5% according to transferrin saturation and 1.5% according to adjusted ferritin." (PMID 33801005, 2021). "The anemia also induced a drop in saturated transferrin concentration, which was recovered similarly by Ferplex® and FeSO4." (PMID 33802720, 2021). "It has also been shown that downregulation of iron-regulated genes, including heparin, ceruloplasmin, transferrin, and transferrin receptors, disrupts the systemic iron homeostasis, leading to anemia in patients with HCC." (PMID 33685417, 2021). "AI usually presents normocytic, normochromic, as mild to moderate anemia with decreased circulating iron concentrations and normal or increased levels of the iron storage protein ferritin while transferrin levels are reduced." (PMID 34835988, 2021). "Mechanistically, copper deficiency reduces iron absorption, leading to decreased loading of iron into transferrin, which eventually blocks the delivery of iron into erythroid cells, resulting in anaemia." (PMID 34390123, 2021). "This included iron level, ferritin and transferrin saturation, which were all significant predictors for anemia." (PMID 32246050, 2020). "In summary, disappearance half-life of intravenous transferrin-bound iron was significantly longer in hereditary hemochromatosis patients compared to the patients with various anemias." (PMID 32041196, 2020). "The main features of anemia of chronic diseases include mild to moderate lowering of hemoglobin level, decreased percentage of reticulocyte count, low iron and transferrin concentration, but increased ferritin." (PMID 32560029, 2020). "The importance of a non-transferrin-dependent iron-regulating system was demonstrated in hpx (atransferrinemic) mice, characterized by anemia and mainly hepatic iron-overload." (PMID 32041196, 2020). "Regarding the 219 patients with normocytic anemia, more than half (n = 125, 57%) presented low iron with low/normal transferrin levels, suggesting ACD." (PMID 33256142, 2020). "Patients with hepatic adenomas and anemia scarcely respond to iron replacement therapy, and have high levels of hepcidin expression and lower serum transferrin saturation." (PMID 32481481, 2020). "Low transferrin values can be found in a variety of pathologies, including anemia of chronic disease, malignancy, infection, and nephrotic syndrome." (PMID 30988354, 2019). "The greatest changes observed after chemotherapy were in transferrin and serotransferrin, which likely reflect disturbances in iron turnover after chemotherapy-induced anaemia." (PMID 31622403, 2019). "The classic sideropenic anemia is severe anemia with microcytic, hypochromic erythrocytes, with low serum iron, decreased transferrin saturation, and very low ferritin level." (PMID 30984307, 2019). "For example, for IBS, CKD or anemia of heart failure, the recommendation to commence therapy is based on a wide range of serum ferritin levels (30–299 ng/mL) and when transferrin saturation is below 20%." (PMID 31614529, 2019). "According to our best knowledge, our results for the first time showed that TMPRSS6 736Val variant is associated with low levels of transferrin and high transferrin saturation in ESRD females with anemia." (PMID 30984307, 2019). "After 72 h, the pigs developed anemia (baseline 9.9 g/dl vs. 72 h, 7.6 g/dl, p = 0.01), characterized by statistically significant decreased iron levels, decreased transferrin saturation, and increased ferritin." (PMID 31346819, 2019).
anemia (continued). "In patients with AI, levels of iron, transferrin and transferrin saturation showed an early decrease compared to controls with a high Hb, already prior to the development of anemia." (PMID 29717382, 2018). "ACD was defined as confirmed anaemia and ferritin levels above 100 μg/l combined with decreased iron and/or reduced transferrin." (PMID 30564730, 2018). "Transferrin and other indices of inflammation, anemia, malnutrition, and oxidative stress were measured in 137 IBD patients (Crohn's disease (CD): n = 63 and ulcerative colitis (UC): n = 74) and 97 controls." (PMID 29226154, 2017). "Nonetheless, transferrin measurement is recommended only in an extensive workup for anemia in IBD patients." (PMID 29226154, 2017). "Higher serum hepcidin quartile was also associated with higher rates of anaemia, treatment with ESA and supplemental iron, and higher serum levels of transferrin saturation (TSAT) and ferritin." (PMID 28652624, 2017). "ID was defined as serum ferritin <100 μg/l, or serum ferritin ≥100 μg/l/<300 μg/l plus transferrin saturation <20%, and anaemia as haemoglobin <13 g/dl (12 g/dl) in men (women)." (PMID 28229219, 2017). "9.16 % (n=11) of cases were reported as IDA by having both anemia and low ferritin and/or low transferrin saturation levels." (PMID 28875005, 2017). "In this study, the iron status of serum ferritin <90 ng/mL and transferrin saturation ≥20% was optimal in hemodialysis patients receiving recombinant human erythropoietin for anemia therapy." (PMID 28662118, 2017). "Of the genetic models of anemia, serum iron concentration and transferrin saturation were elevated in Hbbth3/+ mice as has been previously reported, but no changes were evident in RBC14 or hbd mice." (PMID 28135344, 2017). "Only the administration of Hamp1 was found to have any effect on the evaluated parameters, leading to significant decreases in red blood cell numbers, hematocrit, circulating serum iron and transferrin saturation, indicating an early onset of anemia." (PMID 27100629, 2016). "Similar significant decreases were observed in red blood cell numbers, hematocrit, serum iron and transferrin saturation in both light and severe anemia groups, although all parameters were consistently lower in the severe anemia group." (PMID 27100629, 2016). "Strong graded associations were also observed between greater anaemia severity and lower mean corpuscular Hb (MCH) levels, lower transferrin concentrations as well as higher ferritin, hepcidin and erythropoietin concentrations." (PMID 26792471, 2016). "Anemia of inflammation is characterized by normocytosis and normochromia, shorter survival of erythrocytes, low serum concentrations of iron and transferrin, and elevated levels of ferritin." (PMID 25311752, 2015). "Anemia, very elevated ferritin, and the lowest transferrin tertile remained statistically significant in adjusted analyses." (PMID 25904736, 2015). "They found that the higher iron supplementation (3 mg/L and 15 mg/L) added at this early timepoint resulted in a reduced frequency of anemia and low transferrin saturation compared with the infants who were given the 1.7 mg/L iron supplementation." (PMID 25888053, 2015). "Anemia workup included complete blood count, ferritin, transferrin saturation, serum levels of folic acid and vitamin B12, and C-reactive protein (CRP) concentration." (PMID 25705682, 2015). "This is in accordance with another study showing that overweight Mexican women had similar anemia and iron status (measured with transferrin saturation) compared to normal weight women." (PMID 25333716, 2014). "Patients with iron deficiency state, determined by serum iron concentration and transferrin saturation, were almost comparable with those having anemia." (PMID 27355045, 2014). "The recently published KDIGO anemia guidelines recommend iron supplementation in patients with a transferrin saturation <30% and a serum ferritin concentration <500 ng/mL." (PMID 25462819, 2014).
anemia (continued). "Both models have the same degree of anemia, low transferrin saturation and low liver iron content (LIC), a phenotype quite similar to that of the iron deficient Tmprss6-/-." (PMID 24847265, 2014). "Although most cell types express TfR1, erythroid precursors are dependent on Tf-TfR1-DMT1 for iron uptake as disruption of Tfrc gene in mice or mice with reduced transferrin developed severe anemia." (PMID 24904417, 2014). "Obesity is characterized by chronic, low-grade, systemic inflammation and anemia of chronic disease with elevated serum ferritin and decreased level of serum iron, transferrin saturation, and hemoglobin." (PMID 24665367, 2014). "Further observations highlighted a significant difference in the prevalence of anaemia between children with abnormal (96.6%; 92.5%) and normal (59.8%; 70.3%) ferritin and transferrin values respectively." (PMID 23497273, 2013). "A further feature of "anemia of chronic inflammation" is raised ferritin coupled with reduced transferrin, a scenario witnessed in our present study." (PMID 22871034, 2012). "Most importantly, the changes in ferritin and transferrin levels correlated with the inflammatory state and anemia in SLE, making them potential markers of disease activity." (PMID 22871034, 2012). "Lab data which allowed further differentiation of the type of anemia were available in 70% of anemic patients, in 34.4% values of iron, ferritin and transferrin saturation had been measured." (PMID 22899905, 2012). "The relationship between ferritin/transferrin levels and inflammatory markers and anemia was next analyzed." (PMID 22871034, 2012). "Transferrin had some diagnostic value as the AUCROC was found to be 0.8, a finding consistent with earlier studies in patients with ID anaemia." (PMID 23675232, 2011). "Transferrin replacement in hpx/hpx mice relieves anemia, decreases parenchymal iron deposition in the liver, and reduces the high rate of iron absorption in the duodenum." (PMID 20631898, 2010). "Only in one dog with FRD negative for fecal blood test, low serum iron (45 μg/dL, reference range 81–220 μg/dL), low transferrin saturation percentage (17.5%, reference range 25–52%), and concurrent mild normocytic anemia (Hct 32%, MCV 62 fL) were found." (PMID 20798868, 2010). "The effect of transferrin on hepcidin is likely mediated by low transferrin-bound iron and/or anemia." (PMID 19107209, 2008). "Laboratory findings in severely malnourished children include low albumin, protein, prealbumin, BUN, cholesterol, transferrin, ferritin, B12, folate, and lymphocyte count and severe anemia." (PMID 16412249, 2006). "Despite anemia, the HD group had higher levels of ferritin and transferrin saturation (TSAT)." (PMID 41282024, 2025). "The aim of the present study was to evaluate the prevalence of anemia, and to report the serum levels of iron, transferrin, ferritin, B12 and folic acid in elite athletes entering the Israeli Olympic team, and to explore the effects of gender and types of sports on these variables." (PMID 41470772, 2025). "Its efficacy in more severe anemia and the predictive value of transferrin saturation (TSAT) remain unclear." (PMID 41541984, 2025). "Collectively, these data evidence specific relationships between iron status, MCHC, and severity of hemolysis in patients with SCD and provide support for a model where increased transferrin saturations contribute to increased intracellular concentrations of sickle HbS and worsening anemia in SCD." (PMID 39659429, 2024). "Notably, important measures such as iron studies (ferritin, transferrin saturation), vitamin B12 levels and reticulocyte count are often useful in the investigation of patients with anemia prior to referral." (PMID 39167626, 2024).
anemia (continued). "The levels of biomarkers of iron metabolism (serum iron, TIBC, and transferrin saturation) also increased from baseline with ziltivekimab compared with placebo, suggesting a potential role for anti-inflammatory therapy in the treatment of anemia in CKD." (PMID 38088558, 2024). "His iron panel was inconclusive but more suggestive of anemia of chronic disease with a normal ferritin of 164 ng/mL, total iron-binding capacity of 269 micrograms per deciliter (mcg/dL), transferrin 212 milligrams per deciliter (mg/dL), and iron saturation of 18 percent." (PMID 39280374, 2024). "Our study reveals that patients requiring higher transfusion volumes (3–4 units) exhibit more severe HF (e.g., lower LVEF, higher NYHA class), regardless of the renal function status; they also present with more severe anemia (lower hemoglobin, iron, transferrin saturation, and hematocrit levels)." (PMID 39685694, 2024). "In these situations, other clinical tests, such as the serum iron, transferrin saturation, soluble transferrin receptor (sTfR), sTfR /log ferritin or C-reactive protein, may be useful adjunctive tests to assist in the diagnosis anemia." (PMID 36823529, 2023). "Similar diagnostic limitations are also seen with the use of transferrin saturations and there is no consensus on the definitions of absolute/functional/inflammatory iron deficiency or anaemia of chronic disease." (PMID 36477695, 2023). "The highest transferrin was observed in group B, celiac patients with severe anemia." (PMID 36778054, 2023). "IRIDA patients have microcytic hypochromic anaemia, low serum iron, and transferrin saturation." (PMID 36604716, 2023). "Accordingly, to prevent and manage anemia during pregnancy, the guidelines suggest that nutritional supplementation be optimized three to six months before conception and that iron, ferritin, and transferrin levels be frequently checked." (PMID 37431342, 2023). "It was also suspected that iron and TF may be lost, especially in proteinuric dogs, which may in part, be responsible for anemia in these dogs with CKD." (PMID 36855344, 2023). "The patients present with hypochromic microcytic anemia, low serum iron levels, normal to high serum ferritin levels, and a low transferrin saturation combined with high hepcidin levels and symptoms related to severe anemia, such as fatigue, palpitations, and exertional dyspnea." (PMID 36986429, 2023). "Also, a positive correlation was found between the transferrin concentrations and indicators of anemia, especially the iron levels." (PMID 37571416, 2023). "Anemia of inflammation, hypoferremia, poor transferrin saturation, and high levels of serum ferritin, hepcidin, lipocalin-2, catalytic iron, and soluble transferrin receptor (in ICU patients) have all been iron-associated changes in COVID-19 from the beginning." (PMID 37763241, 2023). "As a result, depressed TF saturation and impaired erythropoiesis may occur, leading to the development of ID anemias typically observed in chronic inflammation." (PMID 37111065, 2023). "High urinary loss of iron and TF along with low TIBC was associated with a degree of proteinuria and may be a contributing factor of anemia in dogs with CKD." (PMID 36855344, 2023). "In the analysis, baseline Hb level ≤ 10 mg/dL (OR, 20.1; 95% CI, 4.71–125, p < 0.001), Ca level < 9.5 mg/dL (OR, 4.28; 95% CI, 1.25–15.2, p = 0.009), and transferrin saturation (TSAT) < 25% (OR, 12.8; 95% CI, 2.51–129, p < 0.001) were associated with anemia improvement." (PMID 36142295, 2022). "Consequently, the iron-binding capacity of transferrin is an important indicator for many diseases, and its measurements are used in the diagnosis and treatment of anaemias." (PMID 36140091, 2022). "The present study reported a normal serum Cu concentration among children of Popokabaka, with 1.5% Cu deficiency prevalence, without being related to anemia, but a negative correlation with transferrin saturation." (PMID 35277041, 2022).
anemia (continued). "Increased levels of transferrin could be due to overload of free iron in the blood which could be indicative of anaemia." (PMID 35902827, 2022). "Yet another reason for alcohol-induced anemia could be related to the levels of circulating transferrin." (PMID 36214835, 2022). "The data, therefore, excludes defective DNM2-dependent CD71-mediated transferrin uptake in EBs as the cause of the severe anemia, as has been described in mice expressing the Dnm2 loss-of-function mutation V235G ubiquitously." (PMID 36110936, 2022). "Meanwhile, uninfected, anaemic children had significantly lower ferritin concentrations and significantly higher transferrin concentrations when compared to healthy uninfected children suggesting that their anaemia may be due, in part, to iron insufficiency." (PMID 35154104, 2022). "In their study conducted in Japan, first trimester Hb levels were significantly better predictors of anemia at T3 than the indices of iron metabolism, including SF, serum iron and transferrin saturation, with an optimal cut-off value of an Hb level at 12.6 g/dL at T1." (PMID 36235743, 2022). "Transferrin was significantly lower in late anemia which in turn could be attributed to the inflammation present in this group." (PMID 35883855, 2022). "These may range from severe anemia with a parenteral iron requirement in infancy to isolated microcytosis and low transferrin saturation with unremarkable anemia in adulthood." (PMID 36295822, 2022). "Laboratory evaluation showed normocytic normochromic anemia (10 g/dl) with increased ferritin and low serum iron, transferrin and transferrin saturation, typical of anemia of inflammation, leukocytosis (13,000/mL, neutrophiles 73%) and high-sensitivity C-reactive protein (158 mg/dl)." (PMID 36175842, 2022). "Higher TSAT in patients with multifactorial anemia may also result from low transferrin levels as a consequence of inflammation (thereby masking the ACD phenotype)." (PMID 34458328, 2021). "First biological tests revealed normocytic non-regenerative anemia associated with hemolysis, thrombocytopenia, and elevated sideremia, ferritin, and transferrin saturation (TSAT) levels." (PMID 34538261, 2021). "Biological tests revealed normocytic non-regenerative anemia associated with hemolysis, thrombocytopenia, and elevated sideremia, ferritin, and transferrin saturation levels." (PMID 34538261, 2021). "However, most patients with SARS-CoV-2 infection presented with normocytic and normochromic anemia and elevated ferritin levels, together with reduced transferrin concentrations, which are hallmarks of anemia of inflammation." (PMID 34677368, 2021). "On the other hand, anticholinergic medications may contribute to the development of anemia by several different mechanisms, mainly represented by inhibition of iron absorption in the stomach and disruption of transferrin signaling." (PMID 34682773, 2021). "Some biomarkers associated with erythropoiesis and the presence of anemia, such as iron, transferrin, ferritin, reticulocytes, and hepcidin, were not included in the original studies and therefore data for these biomarkers were not available." (PMID 34258337, 2021). "Laboratory diagnosis of CA revealed mean hemoglobin levels in the mild anemia range and in the same way the iron kinetics parameters (trend for reduced ferritin, transferrin, and serum iron and increased TIBC) in almost half of the patients assessed in this study." (PMID 34104130, 2021). "Induction of iron restriction utilizing transferrin infusions, minihepcidins, or manipulating the hepcidin pathway prevents iron overload, redistributes iron from parenchymal cells to macrophage stores, and partially controls anemia in β-thalassemic mice." (PMID 34766559, 2021). "Anemia was correlated positively with changes in the BMI z-score, body weight, and serum albumin and cholesterol levels, but correlated negatively with serum calcium, iPTH, ferritin levels, and transferrin saturation." (PMID 30700016, 2019).